CCL4 (C-C motif chemokine ligand 4)
Diseases named in the same sentence as CCL4 in open-access papers (continued):
Sharing a sentence is not in itself a finding about the gene and the disease.
tumor (continued). "CCL3 and CCL4 chemoattract the infiltration of neutrophils, macrophages, natural killer cells, and T cells to the tumor microenvironment." (PMID 36046113, 2021). "First, the patrolling dendritic cells (DCs) are recruited to tumor lesions through inflammatory chemokines (such as CCL4) produced from tumors in early tumorigenesis." (PMID 34138315, 2021). "Activation of this pathway in the tumor impedes the expression of CCL4, which reduces infiltration of DCs in the tumor." (PMID 34439191, 2021). "Wnt can specifically attenuate anti-tumor immunity by decreasing the expression of CCL4, which is a potent chemoattractant, thus preventing the recruitment of DCs and T cells to the TME and blocking adaptive anti-tumor immunity." (PMID 34322780, 2021). "Alterations in β-catenin/WNT signaling caused decreased CCL4 production, which led to diminished infiltration of CD103 + dendritic cells and impaired anti-tumor immune responses." (PMID 34376710, 2021). "Quantitative analysis of tumor RNA detected a decrease in β-catenin gene expression as well as a concomitant increase in CCL4 expression." (PMID 33672668, 2021). "We also tested the impact of CXCL1/IL10/CCL4 on the colony forming ability of PC cells; this in vitro technique examines the capability of tumour cells to form large colonies." (PMID 34359731, 2021). "In mouse melanoma models, tumor-infiltrating basophils seemed to increase infiltration of CD8+ T cells by producing chemokines CCL3 and CCL4, leading to tumor rejection after depletion of Treg cells." (PMID 34209038, 2021). "In the large majority of tumor types, Il12b, Ifng, Ccl4, Ccl5, Cxcl9, and Cxcl10 showed a significant positive correlation with infiltration of M1 macrophages, with Ccl3 displaying a lesser overall correlation." (PMID 34446712, 2021). "Nevertheless, further research is needed to investigate the underlying mechanism of the specific immune-related biological process CCL4 involved in remodeling tumor microenvironment characteristics and driving immunotherapy response." (PMID 34900664, 2021). "In Tnull, the common clusters expressing CCL4 were C11, C07, C12, and C14, except the additional cluster C02 targeting PD-L1high tumor cells." (PMID 33754038, 2021). "There is evidence that CCL4 indirectly promotes cancer development and progression by recruiting certain immune cells and by influencing cells of the tumour microenvironment to enhance their pro-tumourigenic capacities." (PMID 34359731, 2021). "Although CCL3 and CCL4 have an anti-cancer effect by causing cytotoxic TIL infiltration to the tumor, they can support the development of the tumor if they act directly on a cancer cell." (PMID 33076281, 2020). "The effect of chronic hypoxia on CCL3/MIP-1α and CCL4/MIP-1β expression in a tumor cell depends on the type of tumor." (PMID 32781743, 2020). "Altogether, CD103+ DC and CCL4-producing tumor cells are enriched in TNBC treated with CBDCA and anti-PD-1 antibodies." (PMID 32194569, 2020). "In vivo, Ccr5-/- CTLs that were co-transferred with WT CTLs showed impaired homing into CCL3/CCL4-secreting tumours and, in contrast to WT CTLs, did not bind fluorescent CCL3." (PMID 33046212, 2020). "MDSCs can induce the chemokines CCL4 and CCL5 to recruit Treg to the tumor sites and cause immunosuppression." (PMID 32823603, 2020). "CCL4 was highly expressed (75–100% of positive staining cells) by both tumour cells and TAMs in TAM-high mUM." (PMID 33008022, 2020). "Last, during the stage of the secondary tumor, the existing effect of neoadjuvant therapy increases CCL4 expressed in the secondary tumor with an unexplored mechanism, which is responsible for recruiting CD103+ DC." (PMID 32194569, 2020). "At the gene level, most tumor-infiltrating MAIT cells expressed CCL4, CCL3, and RGS1, indicating a high response to inflammation." (PMID 33205061, 2020).
tumor (continued). "It has been reported that CCL4 secreted by cancer cells is critical for the recruitment of CD103+ DC in the tumor microenvironment, and the further anti-tumor effect." (PMID 32194569, 2020). "The herein observed anti-PD-1/G007-LK-induced anti-tumor effect cannot be attributed to enhanced CCL4 secretion." (PMID 32332858, 2020). "Tumor-infiltrating M-MDSCs produce CCR5 ligands CCL3, CCL4, and CCL5, and meanwhile, Tregs exhibit high surface expression of CCR5 and are recruited to tumor tissue by CCL4 and CCL5." (PMID 32793192, 2020). "It has also been demonstrated that MDSC arising from the bone marrow are recruited to the tumor through blood circulation, and that tumor infiltrating M-MDSC mediate the recruitment of Treg in tumor-bearing mice via CCL4 and CCL5 production." (PMID 33603754, 2020). "This profile includes XCL1, mainly secreted by tumor resident CD56low NK cells, and CCL4 and CCL5 mostly produced by CD56low and CD56high NK cells and CD8+ T cells." (PMID 33679726, 2020). "A research had demonstrated that tumor-infiltrating Tregs were increased by doing intratumoral injection of CCL4 or CCL5 in mice models." (PMID 33173412, 2020). "The expression of chemokines for CCR2 (Ccl2 and Ccl7) or CCR5 (Ccl3, Ccl4, and Ccl5) in tumor-bearing lungs, chemoattractants for monocytes/macrophages, was unchanged in FROUNT-cKO mice." (PMID 32001710, 2020). "Activation of the WNT/β-catenin pathway downregulates CCL4 expression by tumor cells and thereby prevents cross-priming of antitumor T cells due to failed recruitment of CD103 + dendritic cells." (PMID 33228231, 2020). "We show that the mechanistic basis for the synergy was not G007-LK-mediated enhanced release of the BATF3-lineage DC-attracting chemokine CCL4 or increased tumor infiltration by CD8+ T cells." (PMID 32332858, 2020). "In accordance with this, the activation of WNT/β-catenin in melanoma cells was shown to result in the ATF3-dependent repression of CCL4 transcription that in turn was correlated with decreased cDC1 numbers at the tumor site." (PMID 32075343, 2020). "This sustainable protection after surgery is CD8+ T cell-dependent, which requires CCL4 expressed in the tumor and involves CD103+ DC recruited by CCL4." (PMID 32194569, 2020). "The administration of an engineered fusion form of the chemokine CCL4 targeting the tumor stroma enhances both DCs and T cell immune infiltration and markedly boosts the responsiveness to ICB in poorly T-cell-infiltrated tumors (cold tumor)." (PMID 32580431, 2020). "WNT/β-catenin signaling induces transcriptional repression of chemokine genes such as CCL4, essential for intratumoral homing of dendritic cells to the tumor bed." (PMID 31447840, 2019). "In particular, CCL4 expression induces recruitment of Batf3 positive dendritic cells which are essential for T cell priming, activation and recruitment to the tumor site." (PMID 31447840, 2019). "It has been shown that tumor-intrinsic active β-catenin signaling results in decreased CCL4 production, which further induces T-cell exclusion and resistance to anti-PD-L1/anti-CTLA-4 monoclonal antibody therapy." (PMID 31221150, 2019). "As such, during chronic filarial infection in humans, Tregs secrete regulatory cytokines like CCL-4 that suppresses tumor-specific and inflammatory responses." (PMID 29483912, 2018). "In fact, in work by Spranger and colleagues, it was demonstrated that the absence of tumor-derived β-catenin signaling allows production of CCL4, a chemokine which aids dendritic cell recruitment and thereby promotes T cell priming and anti-tumor responses." (PMID 29780391, 2018). "β-catenin suppressed CCL4 secretion, which is important for the recruitment of T cells/DCs into the tumor bed." (PMID 30135516, 2018). "Decrease in CCL4 as well as IFNγ with penfluridol treatment was also observed indicating decrease in overall tumor inflammation." (PMID 28512255, 2017).
tumor (continued). "The results showed that several genes were highly expressed in tumor, including Cxcl2, Ccl2, Ccl3, Ccl4, and Ccl5." (PMID 28432279, 2017). "CCL4 induced tumor growth through regulation of antitumor immune responses by a network of MDSCs and Tregs within the tumor microenvironment." (PMID 28404909, 2017). "In our current study, we observed that penfluridol treatment reduced infiltrating human CCL4 in the tumor microenvironment by 54% in SCID-NOD mice injected with human PBMCs." (PMID 28512255, 2017). "We suggested tobacco smoking and betel nut chewing induce increased expression of CCL4 and result in augmented inflammatory response toward tumor promotion and deteriorate anti-tumor immunity." (PMID 28404909, 2017). "Patients with A/G genotype CCL4 rs10491121 correlated with a significantly lower tumor size and trend well cell differentiated grade compared with patients with A/A alleles." (PMID 28404909, 2017). "Our results demonstrated that penfluridol treatment resulted in 54% and 49% reduction of CCL4 and IFNγ respectively, indicating suppression of inflammation in the tumor microenvironment." (PMID 28512255, 2017). "The CCL4 treatment plus CUDR excessive HESCDHs were transformed into tumor in the mouse injury liver (0.251 ± 0.065 gram, n = 8), as well as the tumor was not produced in the rest groups at all." (PMID 27833137, 2016). "CDDO-Me also inhibited expression of chemokines that mediate selective recruitment of TAMs and M2 macrophages, (CCL3, CCL4, and eotaxin) and monocytic infiltration of tumor sites (CCL2 and CCL5)." (PMID 26918785, 2016). "CCL3, CCL4, and IL-1β expression was higher in the adipose tissue and tumor tissue in the cachectic group." (PMID 26732354, 2015). "To our knowledge, we are the first to show that the subcutaneous adipose tissue of cachectic patients presents higher CCL4 protein content in relation to WSC with matched tumor diagnosis." (PMID 26732354, 2015). "Recognizing the interplay between sCD163, which acts as a surrogate of CD-163 positive TAMs burden, with CCL2 and CCL4 that enforce TAMs’ tumor infiltration, could reveal new biomarkers." (PMID 39996747, 2025). "Furthermore, we found higher levels of CXCL10, IL-9, and CCL4 in cases with higher numbers of T cells in direct contact with tumor cells, and thus their potential targets, while in these cases, VEGF levels were reduced." (PMID 40497965, 2025). "Interestingly, the scRNA‐seq data revealed the upregulation of CXCL2, CXCL3, CXCL8, and CCL4 in metastatic tumor cells compared to primary tumor cells or normal cells." (PMID 39985269, 2025). "Tumor-cell-derived CCL4 and CCL2 can enhance TAM infiltration, leading to cancer progression." (PMID 39996747, 2025). "Evidence suggests that CCL4 may also promote tumor growth and progression by attracting regulatory T cells and pro-tumorigenic macrophages." (PMID 39813538, 2025). "Likewise, in the flank tumor model, neutralization of IFN-γ and TNF-α resulted in a significant reduction of CCL3 and CCL4 by CD8+ T cells in the tumor bed of LLCova-bearing mice." (PMID 40553564, 2025). "Tumor‐derived CCL4 also facilitates the recruitment of cDC1s." (PMID 40667699, 2025). "However, the top five downregulated genes in state 5 predominantly include members of the C-C motif chemokine ligand family (CCL3, CCL4L2, and CCL4), which augment tumor immunity by attracting lymphocytes and macrophages." (PMID 38993839, 2024). "It seems that the potential effects of CCL4 on angiogenesis may be also different between pathological tumor angiogenesis and the natural aging as that shown in the present study." (PMID 38739303, 2024). "Ccl3 and Ccl4 were the most upregulated genes related to the regulation of cell communication in shNKX2‐1 tumor‐infiltrated neutrophils when compared to the shCtrl tumor‐infiltrated neutrophils, which was consistent with our initial observations." (PMID 39113226, 2024).
tumor (continued). "In studies in a mouse model of melanoma, β-catenin signalling within the tumour prevented the recruitment of dendritic cells (DCs) by inhibiting the expression of the chemokine CCL4, which in turn impeded the process of T-cell activation against tumour antigens." (PMID 39184916, 2024). "In the tumor immune microenvironment, CCL4 can mediate and recruit the directed migration of key immune cells such as monocytes, macrophages, natural killer (NK) cells, and T cells, which makes it a potentially important element affecting the efficacy of immunotherapy and has specific value." (PMID 39318254, 2024). "Additionally, in silico tumor simulations demonstrated that CCL3 and CCL4 attract CTLs into the tumor, and the newly arriving CTLs amplify chemokine production and promote a positive feedback loop of recruitment." (PMID 38709823, 2024). "In both cases, KCs represented the majority of macrophages in normal liver, but a minor subset in tumoural liver, and expressed higher ID3, lower SIRPA and higher chemokine (CCL4, CCL3) and cytokines genes (IL18) in comparison to CD14+TIM4− tumour-associated macrophages." (PMID 38326607, 2024). "The down-regulation of CCL-4 by Wnt/β-catenin results in reduced tumor infiltration by c-DC1." (PMID 39609700, 2024). "Since CCL4 mainly recruits CD4+ T cells, CCL4 upregulation may lead to a greater proportion of infiltrating regulatory T (Treg) cells in the tumor and enhance local immunosuppression." (PMID 39483474, 2024). "In the study, we found that a new population of CD3+C1q+TAM regulated the anti-tumor immunity of the tumor-infiltrated CD8+CCL4+T cells through the C1q signaling pathway and subsequent metabolic and epigenetic remodeling, thereby potentially affecting tumor prognosis." (PMID 36845133, 2023). "These include increased tumor expression of CCR7 that indicates poor prognosis in mccRCC patients treated with TKIs and increased CXCR4, CXCL5, CCL4, CCL22, and IL-1, which have been linked to poor outcomes by promoting high proliferation rates/aggressive phenotypes." (PMID 38067341, 2023). "Additionally, high levels of CCL4 in the tumor microenvironment predict unfavorable survival in LUAD." (PMID 37626750, 2023). "Tracing the effect of CCL4, tumor markers AFP and GGT were analyzed in sera of animals." (PMID 37835585, 2023). "As CCR5 binds with high affinity to several ligands that are induced by current BCa therapies (CCL5, CCL3 (MIP-1a), and CCL4 (MIP-1b), CCR5i may augment anti-tumor immune responses." (PMID 37759462, 2023). "Moreover, a new population, CD3+C1q+ tumor-associated macrophages (TAM) were identified and found significantly interacted with CD8+ CCL4+T cells." (PMID 36845133, 2023). "However, the role of CCL3 and CCL4 appears to exert both antitumor and pro-tumor behavior which is context dependent in solid cancers." (PMID 36639681, 2023). "The high expression of CCL4 is also related with higher tumor mutation burden level in KIRC 29, which might further contribute to the remodeling of tumor microenvironment." (PMID 37484803, 2023). "These genes include markers of alternative macrophage polarization (Arg1, Cd163), monocyte chemoattractant Ccl6, and ligands for CCR2 (Ccl2, Ccl7, Ccl12) and CCR5/1 (Ccl3, CCl4, Ccl9) suggesting that F4/80+ cells in these tumours represent an increase in TAM2‐like myeloid cells." (PMID 35924447, 2023). "Since CCL4 is a chemoattractant for the recruitment of immune cells with potential anti-tumoral activity such as NK and “naïve” T-cells, the decrease in CCL4 translates into a reduction of T-cell proliferation, activation, and infiltration into the tumor." (PMID 36613445, 2022). "Tumor cells are reported to be one of the major sources of CCL4 in tumor tissues." (PMID 35793868, 2022). "As a chemokine, CCL4 is essential for the immune response in the tumor microenvironment." (PMID 36131790, 2022). "In addition, we observed a significant correlation between levels of CCL4 and Angpt2 expression in tumor specimens." (PMID 35884919, 2022).
tumor (continued). "Tumor-derived CCL4 can recruit CD103+ into the tumor microenvironment." (PMID 35626062, 2022). "While the direct antitumor application has not succeeded yet, several Wnt/β-catenin signaling inhibitors show the potential for enhanced immunotherapy, likely due to their capability to remodel tumor immune microenvironment, especially promoting DCs infiltration by recovering the excretion of CCL4." (PMID 36157510, 2022). "Univariate analysis revealed that higher pathological N status according to AJCC tumor-node-metastasis (TNM) classification was significantly correlated with higher CCL4 and ANGPT2 expression; only ANGPT2 expression was positively correlated with pathological T status." (PMID 35884919, 2022). "Overall, the described involvement of the CCR5 ligands CCL5 and CCL3 in CRC-driven immune escape mechanisms and their tumor-promoting properties seemed to outweigh the capacity of CCL4 to trigger the recruitment of peripheral effector T cells in CRC metastases via CCR5 engagement." (PMID 36428508, 2022). "The SCD1 inhibitor significantly enhanced CCL4 gene expression in these tumor cells, which was canceled by the addition of oleic acid, an unsaturated fatty acid produced by SCD1, indicating that oleic acid is involved in the regulation of CCL4 expression in these tumor cells." (PMID 35793868, 2022). "CCL3 and CCL4 are well-known chemotactic factors influencing tumor macrophage populations." (PMID 35939336, 2022). "Moreover, tumor growth inhibition was inversely correlated with levels of CCL4, CCL5, and MDSCs after treatment with EVT801, either alone or combined with ICT." (PMID 36970050, 2022). "In this study, the tumor purity of the CCL4 high group was lower than that of the low group." (PMID 34900664, 2021). "Since tumor PD-L1 may affect chemokine secretion and cell recruitment, the expression of CCL4, which was expressed similarly between Tnull and TCR-TMART-1 targeting PD-L1low-, PD-L1int-, and PD-L1high-expressing tumor cells, was chosen for analysis." (PMID 33754038, 2021). "The expression of CCL4 and CCR5 was more diverse in TCR-TMART-1 than in Tnull, and CCL4 might recruit different cell clusters with the increasing tumor PD-L1." (PMID 33754038, 2021). "However, in HCC with CTNNB1 gene mutations, the recruitment of pro-inflammatory dendritic cells and, therefore, T cells to the tumor is abrogated by suppressing the production of chemokines CCL4 or CCL5 by tumor cells." (PMID 34632251, 2021). "Another critically important player in the tumor microenvironment is chemokine C-C motif ligand 4 (CCL4), which can both facilitate protumorigenic capacities and also enhance tumor immunity, depending on its interactions with C-C chemokine receptor type 5 (CCR5)." (PMID 34884541, 2021). "We found that single administration of recombinant IL10, CXCL1 or CCL4 attenuates the proliferation of PC cells, and simultaneously induces pro-apoptotic effects, while the stimulation of these cells with a combination of CXCL1/IL10/CCL4 synergistically increased the observed anti-tumour effects." (PMID 34359731, 2021). "Furthermore, we measured the circulatory and tumor associated levels of CCR5 and its ligands (CCL3, CCL4, CCL5) in serum (ELISA), primary tumors (qRT-PCR; IHC) and matched liver metastases (IHC) from CRC patients to assess potential morbidity-related changes." (PMID 32902795, 2021). "We concluded that CCL4 might promote tumor progression in ccRCC and serve as an immune-related prognostic biomarker to predict clinical outcomes and immunotherapy response." (PMID 34900664, 2021). "Activation of Wnt/β-catenin pathway in cancer cells inhibits secretion of CCL4 that is required for the recruitment of BATF-3 dependent dendritic cells to the tumor micro-environment, resulting in reduced levels of DC-derived CXCL10 and limited CD8+ CTL infiltration and cross-priming." (PMID 34774008, 2021).